SNAI2 (snail family transcriptional repressor 2)
Diseases named in the same sentence as SNAI2 in open-access papers (continued):
Sharing a sentence is not in itself a finding about the gene and the disease.
tumor (continued). "GSCs transfected with oe-SNAI2 + oe-PHLPP2 led to notably decreased p-Akt level relative to oe-SNAI2 and increased p-Akt level relative to oe-PHLPP2 in nude mice xenografted with tumor." (PMID 35654777, 2022). "Moreover, based on the expression of EMT hallmark genes including SNAI2, N-cadherin, Vimentin, ZEB1, ZEB2, SNAI1, Fibronectin, TWIST1 and E-cadherin, we found that patients with high risk score distinctly exhibited a mesenchymal phenotype, suggesting a higher tumor malignancy." (PMID 36505846, 2022). "LOX and SNAI2 can regulate the induction of TIMP-4, which can lead to tumor invasion, migration, and VEGF expression." (PMID 35954348, 2022). "To further characterize the role of EMT in tumor progression, we analyzed the expression of EMT markers ZEB2, SNAI2, and β-catenin in an experimental 3D tumor stroma." (PMID 36552039, 2022). "Similar to SNAI2, the expression of CD24 dropped with the addition of tumor cells and reached its lowest point in SCCs." (PMID 36552039, 2022). "Once SNAI2 is overexpressed, it can transcriptionally repress ELF3-AS1 expression, thereby maintaining self-overexpression state in tumor metastasis." (PMID 36457025, 2022). "GSCs transfected with oe-SNAI2 + oe-PHLPP2 led to marked reduction in tumor weight and volume relative to oe-SNAI2 and increased tumor weight and volume relative to oe-PHLPP2 in nude mice xenografted with tumor." (PMID 35654777, 2022). "GSCs transfected with oe-NC, oe-SNAI2, oe-PHLPP2, or oe-SNAI2 + oe-PHLPP2 plasmids were subcutaneously injected into the nude mice, with the tumor volume measured on a weekly basis." (PMID 35654777, 2022). "Through the Comparative Toxicogenomics Database—CTD database—among the 15 EMT genes described, four genes (MMP2, MAP1B, SNAI2, and WNT5A) were related to neoplasms and brain disorders, named neuronal EMT-related genes." (PMID 36553576, 2022). "The findings in our cohort also show that Twist1 and Snai2 can be activated independently in both UC and UCOGC, given that in some cases only, one of these markers is expressed in tumor cells." (PMID 32661742, 2021). "In BC lines and native tumor cells, VEGF-A activates SOX2expression, which leads to SNAI2 induction through miR-452,EMT activation, and increased invasion and metastasis." (PMID 33959388, 2021). "Enhanced CCA migration was associated with induction in key EMT genes and several crucial EMT genes and inducers of EMT such as GLI, PTCHD1, SNAI1, SNAI2, and SHH, in tumor cells in response to inflamed LECs." (PMID 34831316, 2021). "This suggests the presence of a partial ZEB2-orchestrated EMT program in COSCC, similarly to the SNAI2-driven partial EMT in HNSCC, which is clearly distinct from full EMT programs or “mesenchymal” tumor signatures derived from bulk tumor sequencing." (PMID 33142242, 2020). "We further compared the mRNA expression of CDH1, CDH2, SNAI1, SNAI2, VIM, TWIST1 between ccRCC tumor samples and adjacent normal tissues respectively based on RNA-sequence data from TCGA database." (PMID 31915310, 2020). "It is well known that SNAI1, SNAI2, ZEB1, ZEB2, TWIST1 and TWIST2 are key transcription factors involved in EMT in various types of cancers, and they contribute to enhanced tumour cell migration, invasion and metastasis capacities." (PMID 32488136, 2020). "For example, Slug (SNAI2), which is a member of the SNAI EMT-TF family, functions as a master regulator and allows cells to enter into the tumor-initiating cell state." (PMID 32059478, 2020). "Two of the clusters have high expression of genes related to mesenchymal phenotype (e.g., CDH2, SNAI2, ZEB1, TWIST1, and VIM) which were assigned as tumor cells with EMT characteristics (EMT+)." (PMID 32988401, 2020). "Transcription factors such as SNAI2 and ZEB1 play a very important role in the process of EMT and tumor formation through inhibition of E-cadherin expression." (PMID 32605257, 2020).
tumor (continued). "TOX3 has been newly identified as a ccRCC suppressor gene as it inhibited tumor cell migration and invasion by repressing the SNAIL members SNAI1 and SNAI2 at the transcriptional level." (PMID 32789468, 2020). "Oncomine datasets demonstrated CDH1, CDH2, SNAI1, SNAI2, VIM, TWIST1 in 20 types of cancers between tumor and normal tissues." (PMID 31915310, 2020). "AXL receptor tyrosine kinase is highly expressed in H1299-sdCSCs and AXL knockdown with siAXLs significantly reduced tumour sphere formation and ALDH1A1 and SNAI2 (Slug) expression." (PMID 32051483, 2020). "Collectively, these data support the assertion that miR-204-5p has key tumor suppressor functions in HNSCC that are largely determined by its ability to silence SUZ12, SNAI2, JAK2 and HDAC1, and thus inhibit clinically aggressive tumors." (PMID 31938073, 2020). "As a tumor metastasis regulator, CAR10 enhances the expression of SNAI1 and SNAI2 via directly sponging miR-30 and miR-203 to promote EMT." (PMID 30617305, 2019). "Another study demonstrated that miR-200 family targets snail family transcriptional repressor 2 (SNAI2/SLUG) directly to inhibit EMT and functions as tumor suppressive miRNAs." (PMID 28783103, 2017). "SNAI2 transformed normal fibroblasts to a CAF-like state and boosted their tumor–supporting role in 3D organotypic culture and in OC xenograft model." (PMID 29041931, 2017). "Immediately after surgery, tumor samples were frozen in liquid nitrogen and stored in a biofreezer at –80°C for assessment of E-cadherin 1 (CDH1), SLUG (SNAI2), and NCAM (NCAM1) by real-time PCR." (PMID 29267504, 2017). "In OC, SNAI2 was previously reported to induced EMT and was correlated with tumor metastasis and angiogenesis." (PMID 29041931, 2017). "The expression levels of SNAI2 and VIM varied across the TCGA sample set, with median levels generally lower in tumour samples compared to control." (PMID 27876705, 2016). "Then, we compared the mRNA levels of several TGF-β-related EMT-regulators including SNAI1, SNAI2, HMGA2, FOSL1, SP1, ZEB1, ZEB2 (SIP1), and TWIST1 in primary tumor tissues of MDA-MB-231-xenografted mice." (PMID 26462028, 2015). "The expression of genes in tumours was low for CD3Z, CD8, CXCL13, SNAI2 and ESR1 (40-DCq <32) and moderate for IGHM, CD4, CXCL9 and FOXP3 (40-DCq 32–35)." (PMID 25970543, 2015). "Screenings as done herein exemplarily for the HMGA2 regulator let-7a and the HMGA2 targets HMGA1, SNAI1, SNAI2 and CDH1 will help to reveal the tumour acting mechanisms." (PMID 24914948, 2014). "More specifically, when comparing tumor versus normal, the observed significant upregulation of miR-200b leads to significant downregulation of the transcription factor SNAI2 (SLUG) and to a consequent downregulation of ZEB1." (PMID 24968068, 2014). "In this study, we reveal that IGF2BP1 enhances mesenchymal-like cell properties in tumor-derived cells by promoting the expression of the transcriptional regulators LEF1 and SLUG (SNAI2)." (PMID 23677615, 2013). "Strikingly, we observed that IGF2BP1-facilitated modulation of tumor cell migration involves IGF2BP1-directed control of LEF1 and SNAI2 expression." (PMID 23677615, 2013). "The highest expression of SNAI2, TWIST1, VIM and lowest expression of CDH1 was found in the CCND1low/ID1high subgroup of tumours (yellow bars)." (PMID 21955753, 2011). "In cancer, such transcription factors, like Snail/SNAI1, Slug/SNAI2 and ZEB1, often become deregulated and promote tumor progression." (PMID 20860828, 2010). "Knockdown of MELK results in reducing tumor cell invasion and migration, likely by diminishing the levels of matrix metalloproteinase 7 (MMP7), N-catenin, twist family BHLH transcription factor 1 (Twist1), and snail family transcriptional repressor 2 (Snai2)." (PMID 41291696, 2025). "Untreated PDXs showed high Ki67 indices but did not reproduce the conspicuous stromal invasion of CDH1low/SNAI2+/CDH2+ cells that characterized the primary tumor." (PMID 40600748, 2025).
tumor (continued). "In addition to E-cadherin, the activation of the snail family transcriptional repressor 2 (SNAI2) and the heightened levels of matrix metalloproteinase 9 (MMP9) are also vital elements involved in EMT throughout tumor progression." (PMID 40108613, 2025). "In patient 2 (primary FL to relapse FL after a 2-year gap), there was a significant increase in Tumor B1 cells (from 2.89% to 74.56%), indicating that TFs enriched in Tumor B1, such as ZEB1, SNAI2, and ID4, may drive FL relapse." (PMID 41238550, 2025). "Furthermore, a parallel study highlighted a Snai2-mediated transcriptional upregulation of NADSYN1, which binds PHB and amplifies tumor-promoting signaling." (PMID 41011271, 2025). "Moreover, the protein levels of SNAI2, EPCAM, β-catenin, c-Myc, and SOX2 were also detected in EPCAMhigh-and EPCAMlow-cell-derived xenografted tumor tissues." (PMID 36674577, 2023). "Conversely, SNAI2 levels were much lower in adjacent tissue relative to tumor tissue, showing its negative correlation with FBXO28 and PKAα expression and/or activity." (PMID 37596321, 2023). "Moreover, in our study, we investigated the association between miR-181a-5p and miR-630 target genes (BCL2, LMO3, PTEN, SNAI2, WIF1) expression and clinicopathological characteristics as well as survival rates of NSCLC patients in tumor tissue." (PMID 37697308, 2023). "While TJP1 expression in tumour cells is repressed in activated EMT, we found that the expression levels of SNAI2 and TWIST1 were significantly decreased in Ex-MaPac107 and the expression of ZEB1 was significantly increased in Ex-MaPac107 compared with Pri-MaPac107." (PMID 37686338, 2023). "The anti-tumour effects of Rec8 are caused by downregulation of cell growth-related genes (G6PD, SLC2A1, NOL3, MCM2, SNAI1, and SNAI2) and also by upregulation of both apoptosis or migration inhibitors (Gadd45G and LDHA) and tumour inhibitors (PinX1, IGFBP3, and ETS2)." (PMID 36139540, 2022). "SNAI2 is also a key regulator during epithelial‐to‐mesenchymal transition (EMT), which is an evolutionarily conserved transcriptional program and contributes significantly to tumor metastasis." (PMID 34792282, 2022). "Previous studies also found that IGFBP2 could accelerate the migration of tumor cells by regulating LEF1 and SNAI2." (PMID 35519620, 2022). "Overexpression of SNAI2 resulted in a significant acceleration of tumor onset compared to the EGFP negative control, albeit milder than SATB2 (MCR:SNAI2 median onset 18 weeks vs 12 weeks for MCR:SATB2)." (PMID 33527896, 2021). "For instance, the epithelial to mesenchymal transition (EMT)-regulators zinc finger E-box- binding homeobox-(ZEB)-1 and -2, snail family transcriptional repressor 2 (SLUG), snail family transcriptional repressor 1 (SNAI1) and TWIST-related protein 1 (TWIST) are critical drivers of tumor progression." (PMID 34439247, 2021). "Our observation of SNAI2, TGFBI and SERPINE1 in the pEMT signatures of squamous-like cancer types suggests that these signatures reflect both inter-tumour and intra-tumour heterogeneity." (PMID 33972543, 2021). "SNAI2 was the least frequently detected gene in blood samples (1/11 BM18, 1/11 LuCaP70, 0/10 LuCaP96 and 1/10 LuCaP105), although it was detected in the majority of tumour specimens (10/11 BM18, 10/11 LuCaP70, 4/10 LuCaP96, 10/10 LuCaP105)." (PMID 34206049, 2021). "In addition, we examined protein levels of several LPS141 tumor-promoting genes (i.e., RUNX1, c-MYC, FOSL2, RUNX2, and SNAI2) after ETC-168 treatment." (PMID 33564073, 2021). "miR-204-5p is a tumor suppressor in HNSCCs, which inhibits tumor growth, metastasis, and stemness by suppressing the signal transducer and activator of transcription 3 (STAT3) signaling and EMT via targeting SNAI2, SUZ12, HDAC1, and JAK2." (PMID 33917482, 2021). "EGCG treatment inhibited tumour sphere formation and ALDH1A1 and SNAI2 (Slug) expression." (PMID 32051483, 2020).
tumor (continued). "Consistent trends were seen in EpRAS tumor cells treated with TGFβ, and in human mammary E cells HMLE overexpressing one of the three EMT-inducing transcription factors (EMT-TFs) – SNAI1 (Snail), SNAI2 (Slug), and TWIST." (PMID 32266244, 2020). "Besides E-cad, activation of the transcription factor SNAI2 and increased expression of vimentin (VIM) have also been found to act as critical factors in implicating EMT during tumor progression." (PMID 32483426, 2020). "Similarly, in tumor tissues from AOM/DSS-treated mice, KLF4 levels were negatively correlated with mesenchymal markers including SNAI2, β-catenin, and vimentin and positively correlated with the epithelial marker E-cadherin." (PMID 32566755, 2019). "In some tumor types, it blocked EMT and tumor progression, while in others induced EMT-TFs expression and EMT, like we observed in the induction of SNAI1, SNAI2 and ZEB1 expression in MCF7 cells after 5-aza treatment alone or in combination with the SIRT1 inhibitor." (PMID 30445998, 2018). "In contrast to CXCL12 and TWIST1 methylation, the epigenetic regulation of the SNAI2 gene was previously determined only in BC cell line models, not in tumour samples." (PMID 30189837, 2018). "Moreover, NKX6.3 directly bound to promoter regions of SNAI2 and VIM and reduced mRNA transcripts of the SNAI2 and VIM genes, which are important for behavioral changes related to the adhesion and migration properties for local tumor invasion." (PMID 27333045, 2016). "In addition, the miR-15a/miR-16-1 cluster upregulates several genes, including NEDD9, Snai2, MALAT1, and VEGF, and leads to the inhibition of tumor progression by enhancing tumor cell survival, metastasis, and the angiogenic properties of MM cells." (PMID 26649299, 2015). "In addition to controlling actin dynamics, IGF2BP1 sustains mesenchymal cell properties and modulates tumor cell migration also through the upregulation of LEF1 and SNAI2." (PMID 23677615, 2013). "Hence, although FN1 and CDH1 are presumably not the key markers involved, these findings supported the view that the role of IGF2BP1 in promoting tumor cell migration and sustaining mesenchymal-like cell morphology involves the upregulation of LEF1 and SNAI2." (PMID 23677615, 2013). "Moreover, SNAI2 is a core regulator of EMT, a key process in cancer pathogenesis and tumour progression by which epithelial cells acquire a mesenchymal phenotype with invasive and migratory properties." (PMID 22894607, 2012). "SNAI2 (alias SLUG) and TWIST2, two key regulators involved in neural crest development and epithelial-mesenchymal transition (EMT), are also highly expressed in this group; these proteins are known to contribute heavily to cell motility and tumor metastasis." (PMID 20178649, 2010). "Furthermore, high HSPB1 expression may have triggered EMT-related genes (SNAI1, SNAI2, SOX10), suggesting a complex dual effect of 2S-13 on tumor plasticity." (PMID 41007338, 2025). "Dot plots demonstrate differential gene expression between the four tumor cell types (Biphasic_glands, Biphasic_spindled, Monophasic and Poorly differentiated), showing an inverse correlation between the expression of CDH1 (high in Biphasic_glands) and SNAI2 (low in Biphasic_glands)." (PMID 41440042, 2025). "SNAI2, TWIST1, and ZEB1 are the key regulatory genes contributing to the EMT process, where SNAI2 silencing substantially inhibits the EMT process, and overexpression of constitutively active TWIST1 in tumour cells promotes the acquisition of conspicuous EMT characteristics." (PMID 37686338, 2023).
tumor (continued). "In the current study, we hypothesize that EMT contributes to PARPi resistance in non-BRCA mutated tumor cells and PARP1 serves as a transcriptional regulator of SNAI2." (PMID 35864202, 2022). "SNAI2 is upstream target of GSK-3β/β-catenin, and SNAI2 upregulation could promote the activation of GSK-3β/β-catenin to mediate the invasion and migration of some tumor cells." (PMID 34966442, 2021). "Notably, in tumor tissues of the CRISPR-CAR10 nude mice model, the knockout of CAR10 also increased miR-30 and miR-203 expression levels and decreased the mRNA and protein expression levels of SNAI1 and SNAI2." (PMID 30617305, 2019). "We studied a retrospective cohort of 160 consecutive surgically treated NSCLC patients with available frozen tumor samples for expression of EMT markers (CDH1, CTNNB1, CDH2, and VIMENTIN), inducers (TGFB1, c‐MET, and CAIX), and transcription factors (EMT‐TF:SNAI1, SNAI2, ZEB1, TWIST1, and TWIST2)." (PMID 29845746, 2018). "Furthermore, in accordance with the heterogeneity of SNAI2 expression in the primary PCa, the strength of the staining of both SOX2 and NOTCH1 was frequently distinct or strong in the tumor cell clusters forming the expansion/invasion front of high-grade PCa foci." (PMID 25686823, 2015). "These genes were significantly upregulated in the group 2 DIPGs relative to the group 1 tumours (GSEA analysis: enrichment score 0.56, FDRq = 0.039, p nominal = 0.034), together with the master epithelial-mesenchymal transition regulators, SNAI1 and SNAI2/Slug genes." (PMID 22389665, 2012). "Although the expression of TWIST1 and SNAI2 correlated with the co-activation of Vimentin and N-cadherin and hence with the initiation of a mesenchymal differentiation program, in our tumor series they failed to correlate significantly with clinical-pathological characteristics." (PMID 22201613, 2011). "Furthermore, the absence of ERα in primary tumors was associated with lung- and brain- but not with bone metastasis, and tumor biopsies from bone metastatic sites displayed the unusual combination of high Runx2/SNAI2 and high ERα expression." (PMID 22151997, 2011). "Interestingly, FC2 displayed the highest correlation with epithelial cells and showed specific expression of tumor epithelial markers KRT8, KRT10, and KRT18, as well as the EMT markers SNAI1 and SNAI2, suggesting that FC2 may have the tumor‐like aggressive potential." (PMID 34459128, 2021). "Statistically significant distribution was found only between SNAI2 expression and NSCLC patients’ tumor histology and lymph nodes status." (PMID 37697308, 2023). "In contrast, none of the genes found in tumor fragments to be regulated by translation (LOX, WISP), abundance (FOXC1, COL5A2, ITGA11) or buffering (SNAI2) were modulated by mTORC1 in U87-MG cells." (PMID 31052505, 2019). "Notably, other important EMT-related markers such as SNAI1, SNAI2, ZEB1, ZEB2 and TWIST1 at the invasive tumor front were not thoroughly examined in these reported studies." (PMID 26214683, 2015).